MMP9 (matrix metallopeptidase 9)
Diseases named in the same sentence as MMP9 in open-access papers (continued):
Sharing a sentence is not in itself a finding about the gene and the disease.
tumor (continued). "Co-culturing with PDSS2-Del2 overexpressed HCC cells stimulates the PI3K/AKT signaling pathway in macrophages, promotes macrophage differentiation towards the M2 type, and induces MMP2/MMP9 secretion, thereby providing a suitable microenvironment for tumor metastasis." (PMID 39695147, 2024). "The treatment resulted in the decreased expression of MMP-9 in the tumor sections, as indicated by immunofluorescence analysis, and MMP-9 also demonstrated reduced protein expression and proteolytic activity, as confirmed by Western blot and gelatin zymography assays." (PMID 39335164, 2024). "Additionally, it prevents tumor invasion by suppressing MMP9 and fascin and increasing the expression of E-Cadherin." (PMID 38461536, 2024). "Compared to the surrounding tissue, the tumor tissue had a higher expression of MMP9." (PMID 39132498, 2024). "Additionally, the MMP9 inhibitor SB-3CT was also found to enhance tumor immunity by decreasing PD-L1 expression and promoting the activation of CD8+ T cells." (PMID 39343952, 2024). "Additionally, the results show a robust antimigratory effect of GATPP+C10 and TPP+C10, reducing the activation pathways linked to tumor progression and reducing the expression of VEGF and MMP-2 and MMP-9, common biomarkers of advanced CRC." (PMID 39272835, 2024). "In addition, MMP-9 produced by tumor cells drives malignant progression and metastasis and high levels of inflammatory cytokines such as TNF-α, IL-1β, Il-6, and IL-8 present in CM can also significantly increase MMP-9 expression." (PMID 39072314, 2024). "MMP-2 and MMP-9 facilitate angiogenesis, which is critical for tumor growth beyond a certain size by providing necessary nutrients and oxygen; these enzymes do this by breaking down the ECM components around blood vessels, thus allowing endothelial cells to migrate and form new blood vessels." (PMID 39858430, 2024). "Furthermore, inhibiting MMP-9 from either the tumor or the stroma was enough to prevent the growth of the primary tumor." (PMID 39858430, 2024). "Observational data from 31 cases of stage III colorectal adenocarcinomas reveal significant but inconsistent MMP9 expression across different tumor cells, with higher levels in poorly and moderately differentiated carcinomas compared to well-differentiated ones." (PMID 39664453, 2024). "Furthermore, these two CAFs also significantly upregulated FMOD and MMP9 in LK0902 tumor cells compared to cocultures with their tumor-matched CAFs." (PMID 38822309, 2024). "MMP9 is known to promote tumor cell invasion and metastasis through degradation of ECM52." (PMID 39143115, 2024). "Finally, a PE-mediated cell killing assay was performed to investigate if the conditional activation of S4-CPAb-PEcat occurs through MMP-9 that is secreted by tumor cells." (PMID 38804305, 2024). "Furthermore, different highly O-glycosylated protein-coding genes, such as mmp9, ecm1 and ankyrin-2, were upregulated in 4T1/Tn+ tumor cells." (PMID 38245559, 2024). "More importantly, knockdown of MMP9 remarkably suppressed ZBTB11-induced tumor metastasis." (PMID 38355937, 2024). "MMP2 and MMP9 are necessary for tumor invasion and metastasis." (PMID 39195454, 2024). "MMP-9 is a marker for pro-tumor neutrophils that distinguishes them from anti-tumor neutrophils." (PMID 39061147, 2024). "The tumorigenicity-related proteins of xenograft tumors detected by immunohistochemistry and fluorescence quantitative RT-PCR assays showed that attenuated ST L forms can reduce the expression of proteins that promote tumor growth and metastasis, such as Lgals9 and MMP9." (PMID 38992056, 2024). "The tumor microenvironment includes several components, such as endothelial cells, immune cells, and extracellular matrix components like matrix metalloproteinase-9 (MMP-9), which facilitates the proliferation of endothelial cells with pro-angiogenic roles." (PMID 39684754, 2024).
tumor (continued). "Furthermore, this study reports that different highly O-glycosylated protein-coding genes, such as mmp9, ecm1, and ankyrin-2 were upregulated in 4T1/Tn+ tumor cells." (PMID 38245559, 2024). "Epigenetic regulation of the MMP9 is related to the tumor migration suppression in PTC." (PMID 38568917, 2024). "From this, targeting components of the IL‐33‐macrophage‐MMP‐9 axis could represent a potential therapeutic approach toward improving anti‐tumor immune therapy." (PMID 38775220, 2024). "Additionally, the expression of matrix metalloproteinase (MMP)-2 and MMP-9 in tumor cells was decreased after DON treatment." (PMID 38386265, 2024). "Potential tumor-suppressor gene GLCE (p < 0.05), tumor-associated tissue-remodeling gene MMP9 (p < 0.001), and differentiation suppressor CD133 (p < 0.01) showed increased gene expression in the adenocarcinoma tissue compared to the neighboring healthy colon tissue." (PMID 39337548, 2024). "Furthermore, through its degradative action on ECM, MMP9 paves the way for the formation of new blood vessels within tumors, which is crucial for tumor blood supply, oxygen delivery, as well as further growth and dissemination." (PMID 38769413, 2024). "MMP-9 has been found to recruit bone-marrow-derived leukocytes in the tumor microenvironment." (PMID 38542199, 2024). "Notably, a significant rapid rise in tumor- and metastases-promoting molecules such as matrix metalloproteinase-9 (MMP-9), interleukin-6 (IL-6), hepatocyte growth factor (HGF), and placental growth factor (PLGF) was observed immediately (2 h) after surgery." (PMID 39451257, 2024). "MMP9 expression within the tumor parenchyma increased by 5-fold in large tumors (P = .028)." (PMID 38887507, 2024). "The overexpression of MMP-2 and MMP-9 has been associated with advanced tumor-node-metastasis (TNM) staging because they play a role in promoting metastasis, invasion and poor differentiation of tumor cells." (PMID 39057397, 2024). "Thus, it can be stated that the main source of MMP-9 in the tumor microenvironment is represented by TAMs." (PMID 38248804, 2024). "We observed a significant reduction of tumor burden by 50% in MMP9-IN-I treated animals." (PMID 38887507, 2024). "By degrading ECM, MMP9 not only alters the physical and chemical environment surrounding tumor cells, thereby promoting tumor cell proliferation and survival, but also influences the tumor immune microenvironment." (PMID 38769413, 2024). "Also, MMP-9 expression in the tumor fibroblasts was found to be directly induced by tumor cell-derived TNF-α, EGF, or TGF-β." (PMID 39351229, 2024). "MMP9 was the best performing individual biomarker (AUC = 0.85) followed by tumor volume." (PMID 38887507, 2024). "Having the knowledge of tumor MMP9 levels preoperatively could improve patient counseling by predicting intraoperative tumor adherence." (PMID 38887507, 2024). "Matrix metalloproteinase 9 (MMP9) contributes to the tumor microenvironment." (PMID 38956384, 2024). "It was observed that the stroma surrounding the tumor overexpresses MMP9, which might be a response to factors released by tumor cells or other components of the tumor microenvironment." (PMID 39664453, 2024). "Moreover, Bai research on pancreatic neuroendocrine tumor cell line BON1 revealed a correlation between decreased MMP-2 and MMP-9 levels and a reduction in tumor invasion and migration." (PMID 38672151, 2024). "Finally, it was demonstrated that the cleavage of the masking unit can occur exclusively through the secreted MMP-9 of tumor cells, using A-431 as an MMP-9 secreting cell line." (PMID 38804305, 2024). "Diffuse JD0G distribution in both spheroid and xenograft SK-N-AS/MMP9 tumor masses." (PMID 39845957, 2024). "The significant decrease in TIMP1 expression in Nw and Ob-TME cancer cells may contribute to tumor progression and elevated production of MMP9, an inducible enzyme that may also play an important role in angiogenesis." (PMID 39072314, 2024).
tumor (continued). "Finally, we generated a xenograft tumor metastasis model to evaluate the role of MMP9 in metastasis in vivo." (PMID 38355937, 2024). "Furthermore, the expression of MMP2 and MMP9 in 4T1 tumor tissue was investigated, with immunohistochemical findings indicating a correlation with COX‐2 expression." (PMID 39554336, 2024). "Additionally, there was a synergistic effect when Mw was combined with Rosiglitazone for PPARγ expression, tumor growth, and MMP-9 expression." (PMID 39534596, 2024). "Furthermore, the suppression of MMP-9 expression inhibits the invasiveness and metastasis of tumor cells, reduces angiogenesis, and hampers cell growth." (PMID 38388902, 2024). "Tie2+ monocytes express a number of tumor-promoting genes including Mmp9, Vegfa, Cxcl12, Tlr4, Nrp1, and Pdgfb at a high level, and their pro-angiogenic potential could be further stimulated by EC-derived factors in the perivascular niche." (PMID 38580870, 2024). "Its principle may inhibit the migratory ability of SW1990 cells by down-regulating the expression of Ki67, PCNA, Vimentin, and MMP-9 as well as up-regulating the expression of E-cadherin, thus exerting its anti-tumor effect." (PMID 39193331, 2024). "Similarly, in a cohort of HCC patients with or without adrenal gland metastasis, SRC‐1 expression and MMP‐9 expression exhibited higher levels in tumours with adrenal gland metastasis than in primary HCC tumours." (PMID 38506084, 2024). "The expression of MMP-9 in untreated SW480 tumor cells was higher than in the treated SW480 group." (PMID 38256960, 2024). "Except for genes that might have been highly expressed in the lymph nodes (CCL21, LTB) and has already previously identified related to tumor metastasis gene (MMP9), we selected GPNMB as target gene for further study." (PMID 38706915, 2024). "To further validate the involvement of the PROS1-AXL axis in the upregulation of macrophage MMP9 via MICA+ tumor cells, we introduced the AXL inhibitor cabozantinib to macrophages stimulated via recombinant human PROS1 protein and co-cultured with IRF1+ Huh7 cells." (PMID 38254761, 2024). "ROC analysis identified both MMP9 and tumor volume as classifying biomarkers." (PMID 38887507, 2024). "MMPs (especially MMP9) stimulate tumor cell proliferation and the production of VEGF and subsequent angiogenesis, while IL-6, IL-1β, and TNF-α, among pro-inflammatory cytokines, support chronic inflammation preceding or associated with tumor." (PMID 38612841, 2024). "For now, it is well established that VEGF, FGF-2, and ANG-2 upregulate MT1-MMP, MMP-2, and MMP-9 expression: consistently, a positive correlation has been observed between the levels of these angiogenic factors and those of MT1-MMP, MMP-2 or MMP-9 in tumor tissues." (PMID 39120324, 2024). "Furthermore, our investigation revealed a notable upregulation of several matrix metalloproteinases (MMPs) in tumor-infiltrating macrophages, including MMP9, MMP12, MMP19, ADAM8, ADAM9, and ADAM17." (PMID 38254761, 2024). "It was shown that some of the studied compounds, along with inhibition of the expression of key genes of the Hh signaling pathway, also reduced the expression of MMP-2 and MMP-9, which should have a general inhibitory effect on the development of the tumor process." (PMID 39274874, 2024). "In vivo experiments revealed co-expression of ICAM1 and MMP9 on tumor cells." (PMID 38907234, 2024). "Hence, we evaluated the expression of MMP2 and MMP9 to further explore the molecular mechanism by which the 3D microenvironment in the MC-B hydrogels regulates tumor aggressiveness in PC." (PMID 39057404, 2024). "Moreover, the expression of E-cadherin was increased and the expression of N-cadherin and MMP-9 was decreased in xenograft tumor tissues with sh-circUCK2 transfection." (PMID 38245591, 2024).
tumor (continued). "Moreover, immunohistochemical staining demonstrated MEP1A and MMP9 protein expression within the tumor gland ducts of the xenograft tumors, with a notably higher percentage of the positively stained area observed in AsPC1‐DPYD tumors than in AsPC1‐LacZ tumors." (PMID 39158384, 2024). "This could play an important role in fine‐tuning MMP9 activity in vivo as MMP9 is dysregulated in tumours with reduced COSMC levels, thereby contributing to the protease's unwanted and detrimental pro‐tumorigenic activities." (PMID 39074261, 2024). "In addition, IHC staining was performed to detect the expression of PCNA, MMP9, and cleaved caspase 3 in tumor tissues." (PMID 38783241, 2024). "Similarly, a previous study reported that the PI3K/Akt/NF-κB/MMP-9 signaling pathway plays an essential role in tumor metastasis and growth." (PMID 39062099, 2024). "MMP9 has been shown to play a crucial role in the angiogenic switch during tumor progression." (PMID 38358826, 2024). "They produce MMP9 within the CRC tumor microenvironment, promoting tumor progression and invasion." (PMID 39664453, 2024). "Furthermore, in melanoma, β2-AR activation by (R, R')-MNF enhances eEF2 phosphorylation, leading to reduced expression of tumor regulators such as EGFR, cyclin A, and MMP-9, thereby suppressing tumor growth and progression." (PMID 39707196, 2024). "Furthermore, our findings are in favor of using TanIIA as an anti-tumor drug on account of its ability to regulate the expression of Bax, Bcl-2 and MMP9." (PMID 39544939, 2024). "Specifically, high expression of MMP9 may be associated with a poorer prognosis, while low expression of CASP3 may further exacerbate the malignancy of the tumor." (PMID 38769413, 2024). "Given that the liver is a common site for systemic metastases from CRC, the effects of MMP-9 PI polyamide treatment on tumor metastasis were analyzed using a well-established liver metastasis model, where CRC cells were injected into the spleens of athymic mice." (PMID 39858430, 2024). "On one hand, elevated MMP9 levels in CRC patients, due to the intrinsic nature of the tumor environment, may predispose these individuals to an increased risk of developing CIPN when subjected to chemotherapy." (PMID 39664453, 2024). "The role of MMP9 in tumor progression is controversial and differs by tumor and cell type." (PMID 38969706, 2024). "For example, TGF-β, FGF2, EGF, and interleukin 6 (IL-6) stimulate cancer cell proliferation; VEGF and platelet-derived growth factor (PDGF) promote angiogenesis; MMP-2 and MMP-9 degrade extracellular stroma; and CCL22 recruits Tregs lymphocytes to cause tumour immunosuppression." (PMID 39337393, 2024). "The PPI network analysis, informed by topological parameters, suggested that PIK3R1, SRC, AR, and MMP9 could be considered as key target genes for the combined anti‐tumor immunity effects of Danggui and Huangqi." (PMID 38863309, 2024). "Additionally, the treatment inhibited MMP9 activity, crucial for tumor metastasis, suggesting BDP as a novel class of Hsp90 inhibitors able to target TNBC." (PMID 38473804, 2024). "Monitoring levels of MMP-2 and MMP-9 in patients could serve as a biomarker to assess the aggressiveness of the tumor, predict prognosis, or evaluate the effectiveness of gelatinase inhibitors as part of the treatment regimen." (PMID 39858430, 2024). "In both brain and tumor samples, relative mRNA expression of key proline cycle enzymes, that is, POX/PRODH, PYCR1, PYCR2, and PYCR3, were evaluated, along with the expression of genes associated with ECM degradation, i.e., PEPD, MMP-2, and MMP-9." (PMID 38275897, 2024). "Further, ablation of neutrophils could slow tumor development and angiogenesis in the same manner as MMP9 inhibition or knockout could." (PMID 38786066, 2024). "Notably, numerous studies have demonstrated that MMP-2 and MMP-9 inhibition undermines tumor metastasis capability." (PMID 39063556, 2024).
tumor (continued). "Production of the VEGF and matrix metalloproteinase-9 (MMP-9) also stimulates tumour angiogenesis." (PMID 38920685, 2024). "Indeed, the treatment of leukemic cells with the specific inhibitor CP1B, derived from calpastatin, affects the expression and secretion of MMP-2/MMP-9, reducing matrix degradation and thus tumor invasion." (PMID 39156707, 2024). "One member, MMP9, is an inducible protease expressed by tumor epithelial cells." (PMID 39065771, 2024). "More metalloproteinase 9 (MMP9) are in metastatic tumor cells." (PMID 38252369, 2024). "Depressed patients and those with higher levels of chronic stress, current stress, and negative effects had increased expression of MMP-9 in tumor-associated macrophages (TAM)." (PMID 38254696, 2024). "Likewise, EMMPRIN stimulates MMP-9 expression in tumor cells, fibroblasts, and monocytes by activating the ERK and NF-κB pathways." (PMID 38672062, 2024). "Notably, the proportion of neutrophils increased in the metastatic samples, transcriptionally resembling tumor-associated neutrophils (TAN), with a high expression of VEGFA, LGALS3, OLR1, PROK2, MMP9, and IL1RN." (PMID 38358826, 2024). "On the other hand, increased expression of MMP9, KLF4, and TGFβ induced by p40 monomer could imply a proclivity towards lung remodeling and a tumor-associated macrophage (TAM) phenotype." (PMID 38435456, 2024). "Notably, we observed the presence of L-R interactions involving PROS1-AXL and CCL15-CCR1 between MICA+ tumor cells and MMP9+ macrophages." (PMID 38254761, 2024). "Furthermore, immunohistochemical analysis revealed a decrease in the expression of MMP9 in the tumor tissues of CMHE-treated mice." (PMID 39161904, 2024). "They showed that the trypsin inhibitor induced necrosis in tumour tissue, simultaneously suppressing the expression of pivotal genes associated with angiogenesis, such as matrix metalloproteinase genes (MMP-2, MMP-9) and vascular endothelial growth factor (VEGF)." (PMID 39247112, 2024). "However, zebrafish and mouse model systems showed that silencing FLNB increased MMP-9 expression in endothelial and cancer cells, which enhanced tumor angiogenesis and VEGF-A secretion, then promoted tumor growth and metastasis." (PMID 38694875, 2024). "The interaction between tumor unmatched CAFs and HNSCC cells in the tumor spheroids is associated with significant changes in the mRNA expression of CAF-specific markers and significant increases in FMOD and MMP9 in tumor cells compared to when cocultured with tumor-matched CAFs." (PMID 38822309, 2024). "The expression of MMP2 and MMP9 are important indicators of the migration ability of tumour cells." (PMID 38877505, 2024). "Moreover, miR-21 stimulates epithelial–mesenchymal transition (EMT) and upregulates the expression of matrix metalloproteinase-2 (MMP-2) and matrix metalloproteinase-9 (MMP-9), promoting tumor metastasis." (PMID 38473877, 2024). "Furthermore, different highly O-glycosylated protein coding genes, such as mmp9, ecm1 and ank2, were upregulated in 4T1/Tn+ tumor cells." (PMID 38245559, 2024). "The inhibition of MMP2/MMP9 by SB-3CT prolongs survival time by promoting anti-tumor immunity." (PMID 38375034, 2024). "Particularly, MMP-2 and MMP-9 are MMPs overexpressed in GBM that are involved in tumor progression." (PMID 38732135, 2024). "Moreover, it was observed that IGF2BP3 increased the expression of MMP9, which stimulates tumor invasion and metastasis via the degradation of the extracellular matrix and is also important for EMT." (PMID 38504159, 2024). "In clinical practice, these fluctuations could limit MMP9’s effectiveness as a universal marker for monitoring tumor response or predicting treatment resistance." (PMID 39664453, 2024). "Furthermore, IHC analysis of tumor samples obtained from the HepG2 tumor-bearing nude mice revealed a reduction in MMP-9 expression upon usenamine A treatment, suggesting the inhibitory effect of usenamine A on the metastatic potential of the tumors in mice." (PMID 38183094, 2024).